STAT3 (signal transducer and activator of transcription 3)
Diseases named in the same sentence as STAT3 in open-access papers (continued):
Sharing a sentence is not in itself a finding about the gene and the disease.
breast cancer (continued). "Stat3 and miR-124 expression was further measured in 10 relapsed (non-responder) and 10 recurrence-free HER2-positive breast cancer patients." (PMID 27815936, 2016). "Recently, it has been shown that methylsulfonylmethane (MSM), a natural compound without any known toxicities, effectively inhibits the STAT3/VEGF and STAT5B/insulin-like growth factor receptor (IGF-1R) pathways in human breast cancer cells." (PMID 24913037, 2014). "These confounding findings need to be explored in detail to determine the role of STAT3 in carcinogenesis of TNBC, which is defined by the lack of ER, PR and low expression of HER2 which represents about 15%–20% of breast cancers." (PMID 24743778, 2014). "Some of the cancer cells or cell lines employed in these studies do not express constitutively phosphorylated STAT3, such as the MDA-MB-453 breast cancer cell line." (PMID 20712901, 2010). "In mammary tumors, to our knowledge, no report has yet been made linking LIF expression to Stat3 activation." (PMID 17925034, 2007). "The inhibition of the STAT3 pathway by carnosol was mediated through the ROS-dependent targeting of STAT3 protein to proteasomal degradation in TNBC MDA-MB-231 and Hs578T cells, and also in non-TNBC MCF-7 and T47D breast cancer cells." (PMID 37507889, 2023). "A study has shown that circulating levels of A-FABP, also known as FABP4, are significantly higher in obese patients with breast cancer than in those without breast cancer, and circulating A-FABP enhances tumor stemness and aggressiveness by activating the IL-6/STAT3/ALDH1 pathway." (PMID 37056351, 2023). "Since WNT and STAT3 share common downstream target genes, such as D-type cyclins and c-MYC, we conclude that activation of both pathways is not required for opioid-mediated breast cancer migration and metastasis." (PMID 33465556, 2021). "To further validate the induction of cancer cell stemness in breast cancer cells overexpressing TrkA, we performed an aldehyde dehydrogenase (ALDH) assay in BT20 TNBC cells after transient transfection with TrkA, with and without STAT3-CA." (PMID 34066153, 2021). "Interestingly, activation of Shc1 has also recently been shown to potentiate STAT3 phosphorylation in breast cancer cells, but a role for the OSMR-Shc1-STAT3 axis in osteoblasts has not been assessed." (PMID 31191537, 2019). "Experiments performed in human colon, hepatic, and breast cancer cell lines (i.e., HCT-116, SNU387, and MDA-MB 468, respectively) indicated that the ectopic expression of CRIF1 without any stimulation greatly increases STAT3 transcriptional activity." (PMID 29914167, 2018). "This is also in line with the finding that the activation state of the tyrosine kinases JAK1, JAK2, and c-Src, which are considered to be responsible for phosphorylation of STAT3 Tyr705, was not significantly inhibited by the presence of 10 or 20 mM STATTIC in breast cancer cells." (PMID 30283459, 2018). "Analysis of The Cancer Genome Atlas database showed that, unlike primary PIK3CA‐wild‐type and HER‐2+ breast carcinomas, PIK3CA‐mutant tumors display increased expression of AXIN2, HGF, STAT3, IGF‐1, and IGF‐2 mRNA and activation of AKT, IGF1‐MTOR, and WNT canonical signaling pathways." (PMID 28296140, 2017). "Interestingly, we observed that the staining patterns of phosphorylated STAT3, STAT3, and survivin were similar in the serial sections of relapsed HER2-positive breast cancer patients, but not in the recurrence-free patients." (PMID 26755645, 2016). "In addition, the strong nuclear staining patterns of phosphorylated STAT3 and survivin, indicative of STAT3 activation, were detected in relapsed HER2-positive breast cancer patients rather than in the recurrence-free patients." (PMID 26755645, 2016). "However, trastuzumab did inhibit Jab1 protein levels in BT-474 breast cancer cells as well as phosphorylation of AKT and Stat3 (data not shown)." (PMID 21689417, 2011).
breast cancer (continued). "Although EGFR was suggested to be one of upstream regulators of PDK-1/AKT and Stat3 pathways, the role of EGFR activation plays in relation to PDK-1/AKT/mTOR/p70S6K/S6 cascade in breast cancers has not been firmly established." (PMID 16288304, 2005). "Additionally, research suggests that the feedback activation of the STAT3 signaling pathway may be the reason why TNBC, unlike other breast cancer subtypes, is not responsive to SAHA treatment." (PMID 40091020, 2025). "Since IL-6Rα and gp130 are required for signal transduction, the previous contradictory results may have been attributed to a lack of receptor expression in tested breast cancer cell lines, or that IL-6’s pleiotropic effects may depend on JAK/STAT3 pathway activation." (PMID 35371975, 2022). "In nontumor MCF12A mammary epithelial cells and MCF7 breast cancer cells, leptin induces a mesenchymal phenotype, ZEB1 expression, and a “switch” from E-cadherin to N-cadherin, as well as the classic CD24-/CD44+ stem signature, and a larger number of spheres through STAT3." (PMID 33334030, 2020). "To further investigate the physiological relevance of miR-124/Stat3 regulation in radiotherapy resistance, we used qPCR to measure the expression of Stat3 and miR-124 in 10 relapsed (non-responder) and 10 recurrence-free HER2-positive breast cancer patients after radiotherapy." (PMID 27815936, 2016). "Another study found that the overexpression of MUC16 induces breast cancer cell proliferation via its interaction with the non-receptor tyrosine kinase JAK2, and this interaction mediates phosphorylation of transcription factor STAT3, which may transactivate c-Jun for Cyclin D1 expression." (PMID 39149564, 2024). "However, in the breast cancer cells over-expressing ETV7, we could not observe this regulatory mechanism, even when STAT3 was activated by the treatment with IL-6, thus demonstrating that there is a putative competitive relationship between ETV7 and STAT3 in the regulation of the TNFRSF1A gene." (PMID 37041130, 2023).
lung carcinoma (1,056 papers, 2007 to 2026). "In NSCLC, targeting the STAT3/VEGF axis can significantly reduce tumor‐associated VEGF, angiogenesis, and vascular permeability in lung cancer cells, indicating the therapeutic significance of inhibiting STAT3." (PMID 40860906, 2025). "In a lung cancer model, the STAT3 inhibitor STX-0119 caused a marked reduction in white blood cell counts, indicating potential immunosuppression and hematologic toxicity." (PMID 41287778, 2025). "Exosomes derived from hypoxic BMSCs contain miRNAs (miR-193a-3p, miR-210-3p and miR-5100), which enhance the expression of markers associated with EMT by activating the STAT3 signaling pathway, thereby promoting the invasion of lung cancer cells." (PMID 39494330, 2024). "In malignancy overexpression of the transcription factor signal-transducer and activator of transcription 3 (STAT3) has been identified in ovarian, pancreatic, gastric, and lung cancer and associated with poor patient outcomes." (PMID 38424636, 2024). "This upregulation in lung cancer cells is caused by lactate via the signal transducer and activator of transcription 3 (STAT3)." (PMID 38731909, 2024). "Lung carcinoma cells have aberrant STAT3 activation, intimately linked to malignancies’ development and dissemination." (PMID 39588118, 2024). "The lung cancer exosome miRNA-19b-3p targets PTPRD-mediated dephosphorylation of STAT3 in macrophages, activates STAT3, and causes M2 polarization in macrophages." (PMID 39065562, 2024). "Suppression of p38 MAPK and STAT3 activation was associated with reduced lung cancer growth in vitro and in animal models." (PMID 36419386, 2023). "The inhibitory action of CUR on the JAK2/STAT3 pathway is implicated in the reduction of tumour spores and the suppression of tumour growth in mice bearing lung cancer xenografts." (PMID 37697969, 2023). "In particular, we focused on the effects of PA on MAPKs and JAK/STAT and showed that ERK1-2, p38, JNK, and the JAK2/STAT3 pathway are implicated in the regulation of lung cancer cell migration by PA." (PMID 37509443, 2023). "Some recent reports suggest that eEF2K forms a complex with STAT3 in lung cancer cells, and the loss of eEF2K can result in decreased expression of STAT3." (PMID 37875468, 2023). "The inhibition of STAT3 with AZD9150 in xenograft models of lung cancer patients was associated with increased anti-tumor activity." (PMID 36899885, 2023). "Abnormal STAT3 activity has been found in a variety of cancers, including lung cancer, and its phosphorylation level is associated with a poor prognosis of lung cancer." (PMID 36559280, 2022). "IL-6/STAT3 signaling has been associated with tumor progression in BC and lung cancer by inducing EMT and angiogenesis." (PMID 35626741, 2022). "The aberrant activation of STAT3 is usually associated with poor tumor differentiation, advanced clinical stage, lymph node metastasis, and drug resistance of lung cancer." (PMID 36559280, 2022). "We next explored the molecular mechanisms underlying STAT3-mediated adaptive survival of ALK-rearranged lung cancer cells by DNA microarray analysis in YHO-1701-treated cells." (PMID 35228642, 2022). "We elucidated molecular mechanisms underlying STAT3-mediated adaptive survival of ALK-rearranged lung cancer cells." (PMID 35228642, 2022). "The level of constitutive STAT3 activation has been linked to lung cancer metastasis, angiogenesis, and resistance to a variety of anti-cancer drugs." (PMID 35745729, 2022). "High phospho‐STAT3 expression is associated with poor prognosis in patients with various types of cancers such as non‐small cell lung cancer, gastric cancer, and colorectal cancer." (PMID 35356799, 2022). "STAT3 overexpression is observed and associated with poor prognosis of solid tumours, such as gastric cancer, lung cancer, gliomas, hepatic cancers, OS, prostate cancer and pancreatic cancer." (PMID 33382511, 2021).
lung carcinoma (continued). "Their data indicated that autophagy was induced upon loss of circHIPK3, via the miR124-3p-STAT3-PRKAA/AMPKa axis in STK11 mutant lung cancer cell lines." (PMID 34295810, 2021). "Our findings identified the oncogenic role of PRMT5 in human lung cancer and elucidated a novel mechanism underlying the modulation of the Smad7‐gp130‐STAT3 axis by PRMT5 in those cancer types with aberrantly hyperactivation of STAT3." (PMID 34026434, 2021). "In several types of cancer, including lung cancer, the malignant transformation is implicated with the STAT3 signaling pathway by constitutively activating the transcription factor signal transducer and STAT3." (PMID 34129726, 2021). "We further demonstrated that CAFs modulate lung cancer cell metastasis through IL-6/STAT3 and KRT8/AKT pathways, however, the underlying mechanism is not fully understood." (PMID 34552063, 2021). "In the present study, we aimed to figure out the association of miR-526b-3p, STAT3, and PD-L1 in cisplatin-resistant lung cancer by collecting clinical information." (PMID 34321456, 2021). "More than 20% of drugs showing a correlation coefficient higher than 0.3 were collected in the stomach cancer cell lines, while only 1.5% of drugs exhibited an association with STAT3 expression in lung cancer." (PMID 32486001, 2020). "IL-6 and STAT3 are implicated in the malignancy of lung cancers, and many studies have attempted to target IL-6/IL-6 receptor for drug development." (PMID 31900385, 2020). "For instance, it has been reported that elevated STAT3 expression is associated with poor prognosis in gastric cancer, lung cancer and live cancer." (PMID 32194797, 2020). "Further support for a tumor suppressing function for STAT3 came from analysis of patient cohorts with breast, colorectal and lung cancers: high levels of STAT3 are associated with a good prognosis." (PMID 32365499, 2020). "STAT3 has been reported to be associated with the survival rate of patients with nonsmall cell lung cancer and AKT has been associated with survival rate in esophageal cancer (Shan, Chen, Wang, Wang, & Fan, 2017)." (PMID 32281236, 2020). "A literature search for information on STAT3 rs744166 polymorphism has yielded few studies on gastric, colon, and lung cancer." (PMID 31781300, 2019). "In line with its role in promoting ubiquitination and proteasomal degradation of nuclear RelA and STAT321–23, PDLIM2 deletion increased while its expression decreased nuclear RelA and STAT3, a hallmark of NF-κB and STAT3 activation, in lung cancer cells." (PMID 31757943, 2019). "STAT3 activation is clearly a factor linked to bad prognosis in patients with lung cancer, liver cancer, renal cell carcinoma (RCC) and gliomas." (PMID 31557897, 2019). "Previous studies reported that STAT3 activation was closely associated with chemoresistance in a number of malignancies including lung cancer and head and neck cancer." (PMID 31841120, 2019). "Elevated STAT3 expression was associated with poor prognosis in gastric cancer, lung cancer, gliomas, hepatic cancer, osteosarcoma, prostate cancer and pancreatic cancer." (PMID 31557897, 2019). "For instance, hyperactivation of STAT3 caused by EGFR inhibitors (STAT3 feedback activation) was shown to mediate resistance in lung cancer, colorectal cancer and glioma." (PMID 31422383, 2019). "In this work, we report the pro-oncogenic role of the FGFR4-388Arg variant in lung cancer; this variant correlates with greater STAT3 and MAPK activation and higher expression of EMT markers in vitro." (PMID 29402970, 2018). "In agreement with a previous report, STAT3 inhibition by LSS-11 partially leads to resistant lung cancer cells susceptible to paclitaxel." (PMID 29072615, 2017). "Previous study showed that GPRC5A deficiency leads to dysregulated STAT3 signaling via EGF-EGFR pathway in lung cancer." (PMID 28270740, 2017).
lung carcinoma (continued). "Significant increase in STAT3 expression in NK cells in lung cancer patients, revealed in our studies, can be associated with c‐kit and c‐myc down‐regulation in the same cells, since STAT3 executes the downstream signaling from these proto‐oncogenes." (PMID 28695716, 2017). "STAT3 activation or high expression was initially reported to be associated with poor prognosis of lung cancer patients." (PMID 29126425, 2017). "Recent studies have demonstrated that TGF-β-mediated cancer metastasis was associated with the activation of STAT3 pathway in colorectal and lung cancer." (PMID 28757590, 2017). "Recent studies have demonstrated that p-STAT3 overexpression is associated with poorer prognosis in patients with gastric cancer, colorectal carcinoma, pancreatic cancer, and lung cancer." (PMID 28797050, 2017). "Altogether, our work has identified that loss of RIP4 enhances STAT3 signaling in lung cancer cells, promoting the expression of ECM remodeling genes and cancer dedifferentiation." (PMID 28574510, 2017). "Additional evidence suggests that IL-17A drives EMT via STAT-3 signaling in lung cancer, perhaps a mechanism to explain the association with poor prognosis." (PMID 28402963, 2017). "STAT3 has been implicated in various cancers, including breast, ovarian, prostate, and lung cancers, as having a regulatory role in cancer development, including transformation, proliferation, EMT, invasion, and metastasis." (PMID 28030809, 2017). "Study has also shown that the suppression of constitutively active STAT3 in ROS dependent manner can cause growth inhibition and apoptosis in lung cancer cells as well as in xenograft models." (PMID 29254150, 2017). "In conclusion, p-STAT3 overexpression is associated with poorer overall survival of lung cancer patients, as well as with a more advanced TNM grade and lymph node metastasis." (PMID 28797050, 2017). "Activated Stat3 signaling, as a consequence, drives tumor growth and underlines resistance to TKIs in advanced lung cancer." (PMID 27419630, 2016). "Regarding to the tumor types, elevated STAT3 expression in tumor tissues were associated with worse OS of gastric cancer, lung cancer, gliomas, hepatic cancer, osteosarcoma, prostate cancer and pancreatic cancer." (PMID 26959884, 2016). "IL-6 levels are elevated in lung cancer patients in cells lines with endothelial growth factor receptor (EGFR) mutations which results in STAT3 elevation." (PMID 26220864, 2015). "Most importantly, when administered intraperitoneally, combination of BSN and paclitaxel significantly decreased the tumor development in a xenograft lung cancer mouse model associated with down-modulation of phospho-STAT3, Ki-67 and CD31." (PMID 25788267, 2015). "Matrix metalloproteinase 1 (MMP-1) is associated with lung cancer growth and invasiveness, and STAT3 aberrantly induces the MMP-1 gene in colorectal carcinomas." (PMID 24833526, 2014). "To date, single-nucleotide polymorphisms (SNPs) in STAT3 have shown significant associations with cervical cancer, nonsmall cell lung cancer, leukemia, prostate cancer, and hepatocellular cancer." (PMID 24864251, 2014). "Several STAT3 SNPs were reported to be significantly associated with cervical cancer, nonsmall cell lung cancer, metastatic renal cell carcinoma, prostate cancer, and hepatocellular cancer." (PMID 24864251, 2014). "The STAT3 target genes have been implicated in a number of cancers, including liver, breast, and lung carcinomas, as well as skin disease and autoimmunity." (PMID 23185365, 2012). "Similarly, miR-210 transferred by lung cancer cell-derived exosomes acts as a proangiogenic factor in cancer-associated fibroblasts by modulating the JAK2/STAT3 pathway." (PMID 36977736, 2023).